AR (androgen receptor)
Diseases named in the same sentence as AR in open-access papers (continued):
Sharing a sentence is not in itself a finding about the gene and the disease.
tumor (continued). "For example, the anti-helminthic niclosamide has been applied as an anti-tumor agent to a variety of cancers, including castrate-resistant prostate cancer androgen receptor variants." (PMID 27438712, 2016). "This scenario would require the AR-GSRs to co-exist on the same AR allele, as these tumours harboured a single AR gene copy." (PMID 27897170, 2016). "Collectively, these results indicate that only a subset of AR-GSR events are associated with tumour-specific AR-V expression." (PMID 27897170, 2016). "It has been indicated that in patients with ER-positive tumor, AR expression was associated with a better outcome." (PMID 27340922, 2016). "Since de novo tumorigenesis is considered to be one of the mechanisms for BC recurrence, we then investigated associations between AR/ERα/ERβ expression in corresponding normal urothelial tissues and tumor recurrence." (PMID 26885620, 2016). "Our results are consistent with a smaller study that found that 21% of 30 BRCA1-associated ER-negative breast cancers expressed the AR using the same criteria of at least 1% of tumor nuclei staining." (PMID 28721372, 2016). "Of these mechanisms, clinical evidence based on detection of constitutively active AR splice variant in circulating tumor cells from patients with CRPC suggests a correlation with resistance to enzalutamide and abiraterone." (PMID 27576691, 2016). "Follow-on studies then linked the effects of AR-12 on tumor cell biology to regulation of the chaperone proteins HSP90, GRP78 and HSP70." (PMID 26887051, 2016). "AR signaling has been implicated in bladder carcinogenesis, as androgen deprivation has been shown to inhibit tumor growth in mouse models and xenografts." (PMID 27437104, 2016). "Docetaxel caused cytoplasmic AR sequestration ex vivo and in circulating tumor cells with significant down-regulation of AR and PSA expressions, so the PSA value seemed not to be useful in CRPC AR-independent." (PMID 27242530, 2016). "AR-positivity was significantly associated with higher tumor stage (p = 0.005) and higher histologic grade (p = 0.002)." (PMID 26249023, 2015). "As the disease advances, the tumour becomes “castration resistant”, with changes in the responsiveness of the androgen receptor (AR) and in its associated signalling pathways." (PMID 25281165, 2015). "There has been much interest in the AR splice variants expressed in tumor cells that are similar in structure to the truncated AR used in this study." (PMID 25950519, 2015). "Differential enriched AR peaks are located mostly in intronic or distal intergenic regions of the genome (Fig3F), and primary tumor-associated AR sites are enriched on chromosomes 16 and 19 (Fig3G)." (PMID 26412853, 2015). "Decreased stromal AR expression in cancer has been associated with tumor resistance to androgen deprivation, and with relapse and progression following radical prostatectomy." (PMID 25965833, 2015). "Mutation of these two sites in AR inhibited Ack1-induced AR transactivation and DNA binding as well as tumor growth." (PMID 25950519, 2015). "After a multivariate analysis tumor size, highly undifferentiated tumors, positive lymph node status, loss of AR and E-cadherin expression were significantly associated with DFS and the OS." (PMID 26039245, 2015). "Current research is focusing on the non-invasive retrieval of tumor DNA from blood/serum samples, i.e. circulating tumor DNA (ctDNA) or DNA from circulating tumor cells (CTC) to analyze aberrant AR variants." (PMID 26325261, 2015). "AR-V expression in patient tissues or circulating tumor cells is associated with resistance to AR-targeting endocrine therapies and poor outcomes." (PMID 25908785, 2015). "By directly competing for androgen binding, anti-androgens such as bicalutamide, prevent activation of the AR and hence cause tumour regression." (PMID 26267320, 2015).
tumor (continued). "AR expression was significantly associated with low stage, well or moderately differentiated tumours, and a favourable outcome, decreasing with tumour growth and dedifferentiation." (PMID 28326246, 2014). "In PJS-associated SCTAT, the serum tumor marker inhibin and immunohistochemical markers inhibin, estrogen receptor, progesterone receptor, and androgen receptor have been studied as diagnostic tools, though morphology is the gold standard." (PMID 25530972, 2014). "This increase of therapeutic efficacy in vivo by AUY922/docetaxel combination was associated with attenuated AR expression and transcription and a significant increase of tumor cell death." (PMID 25072314, 2014). "Altogether, these data suggest a role for tumor-associated over-expression of NWD1 in dysregulation of AR signaling in PCa." (PMID 24681825, 2014). "Positive androgen receptor immunoreactivity was inversely correlated with tumor grade (p<0.01) and associated with better overall patient survival (p = 0.032) in the non-basal triple negative cancer group." (PMID 24505496, 2014). "Alternatively, support for LCH as a neoplasm is based on publications that have shown clonality of the CD1a+ cells in LCH using the human androgen receptor assay and BRAF mutation studies." (PMID 25343480, 2014). "Sections of tumor tissue displayed loss of nuclear AR expression, whereas other sections remained with nuclear AR expression." (PMID 25072314, 2014). "High expression of NWD1 (median cut-off) was associated with areas of AR positive immunostaining in 75% of hormone refractory tumor samples (15/20)." (PMID 24681825, 2014). "By univariate analyses, the tumor size, ER percent staining and AR:ER ratio were significantly associated with all survival outcomes, while nodal positivity was significant only for tamoxifen failure and DFS." (PMID 24451109, 2014). "Our PCa mouse model clearly demonstrated that increased CCL2 and EMT markers in AR silenced PCa cells were associated with increased distant metastasis, in spite of reduced size of orthotopic AR silenced primary tumours." (PMID 23982944, 2013). "Many possible mechanisms have been proposed for CRPC, such as super-sensitivity of tumor cells to low levels of androgen, intratumoral androgen para-/autocrine production, AR mutation and ligand independent AR activation." (PMID 23880851, 2013). "Beyond the AR alterations in advanced tumors, three of the most common genetic alterations in PCa are: overexpression of Myc, loss of the tumor suppressor Pten, and fusion of Ets genes with upstream AR regulated promoter sequences (e.g., TMPRSS2-Erg)." (PMID 24199173, 2013). "In spite of some studies suggest that constitutively active AR variants have an impact on tumor progression, their function remains so far unresolved." (PMID 23658830, 2013). "Clonality assays, which are based on X-chromosome inactivation mosaicism and polymorphisms at the PGK and AR loci in female somatic cells, are a very important means of differentiating neoplasm from reactive hyperplasia." (PMID 23958352, 2013). "The aim of this study was to investigate the impact of constitutively active AR variants on the expression of tumor progression markers." (PMID 23658830, 2013). "The aim of this work was to show a possible link between the presence of constitutively active AR variants and the expression of tumor progression markers." (PMID 23658830, 2013). "Another important mechanism driving castration-resistance is mutation of the AR gene, the frequency of which increases with tumor stage and in CRPC." (PMID 23674566, 2013). "This study indicated that genistein at low, physiologically relevant exposure levels can be an endocrine disruptor and can result in altered activity of multiple tumor-derived mutant AR alleles." (PMID 24167630, 2013).
tumor (continued). "AR oncogenic action has been extensively studied: in tumor cells AR activation can cause proliferation and block apoptosis, suggesting that altered context enables AR to support cell growth." (PMID 22403609, 2012). "Our group showed that in AR-null PC-3 cells inducible AR expression causes androgen-dependent tumor suppression, accompanied by decreased angiogenesis." (PMID 22403609, 2012). "Recent study shows that approximately 50% of AR mutations induced by androgen ablation reduce or abolish its transactivation activity, also suggesting tumor suppressive function." (PMID 22403609, 2012). "AR positivity was found associated with favorable tumor characteristics, such as small tumor size, low histological grade, ER- and progesterone receptor (PR)-positive status, and with better outcomes than in patients with AR-negative tumors." (PMID 23241075, 2012). "The positive expression of the four receptors all correlated with high tumor grade and intestinal type, and ERα and AR were also associated with early TNM stage and thereby a favorable outcome." (PMID 23199240, 2012). "While growth-inhibitory, tumor-suppressive AR effects have also been documented, the underlying mechanisms are poorly understood." (PMID 22403609, 2012). "Although IRS2 has been positively associated with aggressive tumor behavior, it has also been identified as a primary target gene of AR." (PMID 22844442, 2012). "AR was expressed in 56% of tumours and expression was significantly inversely associated with 10-year survival (P = 0.004)." (PMID 22471922, 2012). "The protein expression of ERα and AR was closely associated with tumor grade, Lauren type, T classification, and N classification (P < 0.001), respectively, and consequently correlated with TNM stage (P < 0.001)." (PMID 23199240, 2012). "All the four receptors were associated with high tumor grade and intestinal type, and the positive expression of ERα and AR also correlated with early TNM stage and thereby a favorable outcome." (PMID 23199240, 2012). "Relationships of AR positivity with low grade, ER-positive and PR-positive status are well documented, and associations with tumor size and axillary nodal involvement have been reported in some studies but not in others." (PMID 23241075, 2012). "MicroRNAs provide an attractive target for furtherinvestigation as they can regulate multiple genes, including AR, and are associatedwith stem cell biology, tumour biology and hormone independence." (PMID 21633508, 2011). "This assumption was mainly based on the Dunning rat tumor model where the development of an androgen-insensitive state is linked to the loss of the AR in tumor cells during androgen withdrawal." (PMID 21980429, 2011). "Although the in vitro development of an androgen-independent phenotype is mostly based on the loss of the AR in tumor cells, there is evidence from several clinical studies that the AR is rarely lost in CRPC cells in vivo." (PMID 21980429, 2011). "This AR-target signature was linked to multiple publicly available cell line and tumor derived PCa databases, revealing that distinct functional clusters were differentially modulated during PCa progression." (PMID 21829708, 2011). "Recent study has revealed a new pathway that Retinoblastoma (RB; encoded by RB1) depletion induced unchecked androgen receptor (AR) activity that underpinned therapeutic bypass and tumor progression." (PMID 21504622, 2011). "NE-like differentiation is associated with a loss of AR expression in both LNCaP cells and human tumours." (PMID 20219091, 2010). "Approximately 30% of recurrent tumours show amplification of the androgen receptor gene with an estimated 10–30% of antiandrogen-treated patients having a mutated androgen receptor." (PMID 19088719, 2009).
tumor (continued). "Treatment of tumors expressing a mutated AR isoform with siRNAs targeting specifically this mutation would silence AR in the tumor, while preserving its expression is normal tissues, thus reducing the unwanted side effects." (PMID 17925854, 2007). "The benefits of these treatments are typically transient, with later tumor growth associated with increases in expression levels of AR or its cofactors, or mutations that render AR resistant to antiandrogens." (PMID 15328534, 2004). "We next examined whether the tumor-associated gene expression differences 20, racial disparity genes 21 and AR-signaling gene differences 22 were also evident in controls." (PMID 41584049, 2026). "Additionally, tumor tissues from patients classified as Normal-like were significantly associated with AR/ESR1 ≥ 2.0, compared to Luminal A tumors (Odds ratio: 0.371; 95% CI: 0.145–0.949; p = 0.039)." (PMID 40593140, 2025). "The AR, a master regulator of male reproductive physiology, exhibits profound heterogeneity across patients and tumor subclones, driven by genetic mutations (e.g., AR-V7 splice variants), post-translational modifications (phosphorylation, acetylation), and epigenetic rewiring." (PMID 41323732, 2025). "The association of the AR status with clinicopathological factors (age, stage, tumor diameter, lymph node invasion, metastatic spread, Ki-67 score, EGFR score, and cytokeratin 5/6 score) and the disease outcome (disease-free survival—DFS—and overall survival—OS) was investigated." (PMID 40150035, 2025). "Moreover, distinct microbial configurations have been associated with differential expression of androgen receptor-regulated transcripts and tumor immune infiltration patterns, suggesting that the microbiome exerts dual control over hormonal and immune axes." (PMID 41384118, 2025). "This suggests that AR expression may be linked to a less aggressive tumor phenotype and could serve as an indicator of tumor differentiation status." (PMID 40734715, 2025). "This occurs due to the development of resistance mechanisms, including amplification or mutation of the androgen receptor (AR) gene, increased expression of AR splice variants, and activation of alternative signaling pathways that regulate tumor growth independently of androgens." (PMID 41347146, 2025). "While NEPC represents a distinct lineage plasticity-driven phenotype, the observation that NO similarly suppresses ER stress and tumor growth in AR-deficient LNCaPAPIPC tumors suggests that its therapeutic potential warrants further investigation in broader AR-independent PCa contexts." (PMID 41198652, 2025). "However, CRPC tumor cells often develop resistance to drugs such as enzalutamide through mechanisms including AR point mutations, AR amplification, alterations in androgen biosynthesis, and other factors." (PMID 40771930, 2025). "Canine models have revealed that AR expression is associated with both benign and malignant tumors, suggesting that ARs may play a role in tumor classification and prognosis in both species." (PMID 40286049, 2025). "Binding of enzalutamide to AR in the cytoplasm inhibits AR translocation into the nucleus, and in the nucleus, enzalutamide inhibits AR binding to the DNA and thereby blocks the transcription of genes associated with tumor progression and survival." (PMID 39781466, 2025). "Furthermore, overexpression of the androgen receptor (AR), along with the emergence of mutated AR variants, contributes to tumor advancement." (PMID 41373813, 2025). "Higher circulating testosterone levels could directly activate tumor AR activities, but tumors can also develop ligand-independent sustained AR activities through mechanisms such as AR mutation, gene amplification, or even intratumoral androgen synthesis." (PMID 41228208, 2025).
tumor (continued). "In each case, a high ENR program was linked to shorter tumor control with AR targeting, and there was a strong suggestion this program was not only prognostic but also predictive of failure to respond to AR targeting with enza or other ARPIs such as abiraterone or ADT alone." (PMID 40624104, 2025). "Downregulation or loss of function of AR may enhance the interaction between tumor cells and the bone microenvironment, promoting bone metastasis 44-46." (PMID 39816691, 2025). "A second study validated the association of high tumor AR levels with poor ESCC patient survival." (PMID 41228208, 2025). "Meanwhile, loss of AR (or ERβ) in tumor specimens may serve as an indicator of high sensitivity to these non-surgical treatments." (PMID 40486871, 2025). "Additionally, the loss of AR expression in ACRJ-PC28 during establishment creates some uncertainty about how closely it represents the original tumor biology." (PMID 41038711, 2025). "However, resistance mechanisms-driven by AR splice variants, tumor plasticity, and immune evasion-remains a critical barrier, particularly in mCRPC, underscore the need for combination regimens and biomarker-guided approaches." (PMID 41200193, 2025). "Therapeutic resistance arises from multiple interconnected factors: AR splice variants (particularly AR-V7) enable ligand-independent AR activity, metabolic reprogramming allows adaptation to therapeutic pressure, and the immunosuppressive tumor microenvironment facilitates treatment evasion." (PMID 41462716, 2025). "Consequently, high tumor AR levels were associated with poor patient survival, especially for smoker patients, consistent with the finding that AR promoted tumor cell proliferation as well as invasion." (PMID 41228208, 2025). "It remains unclear, however, whether these genetic variants directly impact AR function or influence androgen-tumor interactions." (PMID 39726664, 2025). "AR overexpression was strongly associated with advanced tumor stage and low survival29220539." (PMID 38966543, 2024). "Furthermore, QRT-PCR to detect AR mRNA transcripts and the AR-v7 splice variant revealed AR and AR-v7 mRNA is significantly depleted in CU-PC01 PDX tumours relative to the positive controls (n = 3), consistent with DNPC." (PMID 38667288, 2024). "Interestingly, loss of tumor suppressors is associated with lineage plasticity, AR-independent tumor growth, and ARPI resistance in pre-clinical models." (PMID 39195285, 2024). "To identify the downstream pathway involved in AR mutation-associated hepatocarcinogenesis, we performed chromatin immunoprecipitation sequencing (ChIP-seq) and RNA sequencing (RNA-seq) on tumor tissues and benign liver tissues from ARQ62L, ARE81Q and ARWT groups." (PMID 38182647, 2024). "AR variants can be detected in circulating tumor cells (CTCs)." (PMID 38339092, 2024). "The phenotyping of the latest mouse model with the crispr-cas9-mediated knockout of ERβ reports a tumor suppressor function in the ventral prostate and mammary epithelium, where the loss of the receptor leads to increased activity of the androgen receptor (AR) and ERα, respectively." (PMID 39175529, 2024). "Similarly, mutations in the FOXA1 gene activate AR signaling, promotes tumor growth, facilitating the epithelial-mesenchymal transition, and increasing tumor metastasis potential by inducing transcriptional changes that activate the WNT signaling pathway." (PMID 39296545, 2024). "BHLHE40 encoding DEC1 mediates cellular senescence by its direct target gene CCNG2, that encodes the atypical and tumor suppressive Cyclin G2, as a novel tumor suppressive axis encompassing androgen receptor-BHLHE40-Cyclin G2 in order to mediate cellular senescence in PCa cells." (PMID 38902772, 2024). "Furthermore, mCRPC patients who exhibit an androgen receptor splice variant (AR-V7) in their circulating tumor cells showed better overall survival outcomes when treated with taxanes compared to ARSI treatments." (PMID 38794139, 2024).